MTOR (mechanistic target of rapamycin kinase)
Diseases named in the same sentence as MTOR in open-access papers (continued):
Sharing a sentence is not in itself a finding about the gene and the disease.
cancer (continued). "The data obtained in this study suggest a potential mechanism by which VC induces cancer cell death by inhibiting the mTOR signaling pathway." (PMID 36787291, 2023). "There is a strong rationale to investigate PIM inhibitors in combination with PI3K/AKT/mTOR pathway inhibitors, as their interactions drive cancer cell proliferation and cell survival." (PMID 37943821, 2023). "Specifically, this enzyme is a key component of the PI3K/AKTs/mTOR signaling pathway, whose overactivation contributes to the development of many human cancers and resistance to chemotherapeutic drugs." (PMID 37513905, 2023). "Bufalin and sorafenib worked effectively and reduced the levels of p-AKT and p-mTOR in SMMC-7721 cancer cells." (PMID 36903477, 2023). "A higher expression (at transcriptional and translational levels) and activity (at a post-translational level) of most members from the PI3K/AKT/mTOR pathway is commonly found in cancer cells—independently of the type of malignancy." (PMID 37047267, 2023). "The aberrant activation of PI3K/AKT/mTOR signaling is a common finding in cancer, in which it plays a pro-survival role." (PMID 37237490, 2023). "The PI3K/Akt/mTOR pathway is known to stimulate cancer cell proliferation by mediating the transition from G1 to S phase during cell cycle progression through the activation of a cell-cycle regulator protein, cyclin D1." (PMID 37046823, 2023). "mTOR has always been considered as an effective cancer therapeutic target, and the mTOR signaling involves complicated feedback networks." (PMID 36691031, 2023). "The PI3K/Akt/mTOR signaling pathway is commonly involved in cell survival, growth, and proliferation in human cancers." (PMID 37089945, 2023). "Based on the important roles played by mTOR signaling in cancer progression, we next performed a Western blot analysis of mTOR pathway components." (PMID 37355516, 2023). "Targeting the PI3K/AKT/mTOR pathway is a validated strategy for cancer treatment because it is aberrantly activated in several human cancers and plays an essential role in cell growth, proliferation, differentiation, and apoptosis." (PMID 37631072, 2023). "It has been reported that activation of the PI3K/AKT/mTOR pathway is relevant to PD-L1 expression and tumor immune microenvironment, implying a novel indication for cancer immunotherapy." (PMID 36960074, 2023). "We confirmed these in silico observations by showing the inhibition of mTOR signaling and cancer cell proliferation in vitro, and increasing lifespan in vivo." (PMID 37175557, 2023). "A group of genes heavily implicated in human cancers are the oncogenic RAS genes, which signal through the RAF-MEK-MAPK and phospho-inositol-3-kinase (PI3K)-AKT-mechanistic target of rapamycin (mTOR) pathways to drive cell growth, proliferation and survival." (PMID 36861754, 2023). "Homoharringtonine, periplocamine, dactolisib, AZD-8055, anisomycin, verrrucarin A, and BX-795 all have effects on the PI3K/Akt/mTOR pathway in different cancer models, contributing to their antitumor activities." (PMID 38132962, 2023). "Recent studies have revealed interplays between miRNAs and the mTOR pathway during cancer development." (PMID 36830073, 2023). "PHF5A knockdown indicated the prohibition of cancer cells via the AKT/mTOR signaling pathway with eventually enhanced apoptosis and reduced proliferation/migration of cancer cells." (PMID 37483794, 2023). "Previous research has highlighted the importance of the PI3K/AKT/mTOR network in mediating communication between HPV-positive cancer cells under normoxic and hypoxic conditions." (PMID 37795297, 2023). "Aberrant mTOR signaling is commonly observed in cancer, making it an interesting therapeutic target." (PMID 37486536, 2023).
cancer (continued). "The PI3K/Akt/mTOR pathway plays a crucial role in cell growth, proliferation and survival, and is frequently dysregulated in cancer." (PMID 37372460, 2023). "On the other hand, enhancing the gene expression of PI3K/Akt/mTOR mediators increases cancer cells’ resistance to chemotherapy." (PMID 36984763, 2023). "AMPKα2 is qualified to manage the mammalian target of rapamycin (mTOR) signaling pathway to control cancer cell cycle arrest." (PMID 36677797, 2023). "The activation of KRAS triggers downstream proteins such as MEK, RAF, PI3K, AKT and mTOR proteins, to induce transcription, endocytosis, migration and metastasis of cancer cells." (PMID 37686543, 2023). "The results revealed that OSBPL3-related genes were associated with mTOR, FoxO, VEGF, MAPK and Ras signaling pathways and pathways linked with cancer and metabolism process." (PMID 37550605, 2023). "Calorie restriction can diminish serum concentrations of IGF-1 with the potential to suppress the PI3K/Akt/mTOR axis and thus glycolysis in cancer cells." (PMID 37527766, 2023). "Some findings suggest that Cu E inhibits the PI3K/AKT/mTOR signaling pathway, leading to the activation of autophagy in human cancer cells and intestinal epithelial cells." (PMID 37886957, 2023). "The anti-cancer activity of this flavonoid has been reported to occur mainly through the inhibition of mTOR signaling." (PMID 37237490, 2023). "The PTEN/PI3K/Akt/mTOR pathway is one of the most frequently overactivated intracellular pathways and involved in proliferation and anti-apoptosis in various cancers." (PMID 37079213, 2023). "These adhesive connections promote the activation of the Akt/mTOR signaling pathway in cancer cells, stimulating their proliferation and leading to the formation of overt bone metastasis." (PMID 38041134, 2023). "One of the most studied therapeutic targets in cancer is mTOR signaling, which plays a role in various cellular processes, including proliferation, differentiation, metabolism, genomic instability, and angiogenesis." (PMID 37894790, 2023). "Best known as a driver of cancer, mTOR is a critical protein kinase that regulates cell growth and metabolism via two multiprotein complexes." (PMID 37457922, 2023). "In parallel, mTOR is hyperactivated in up to 80% of cancers, founding the use of mTOR inhibitors as antiproliferative drugs in chemotherapies in other cancer types." (PMID 37628917, 2023). "For instance, the bioflavonoid quercetin can inhibit proteasome activity in human cancer cells, thereby triggering macroautophagy and blocking mTOR activity in human cancer cells." (PMID 36830086, 2023). "Its efficacy in treating these malignancies prompted the scientific world to investigate its impact on cancers having dysregulation of the critical PI3K/Akt/mTOR pathway." (PMID 37513916, 2023). "AMPK and PI3K/Akt/mTOR pathways under incorrect modulation characterise cancer stem cells and, for this reason, are considered important therapeutic targets." (PMID 37368660, 2023). "In many cancers, mTOR exhibits hyperactivity and functions as an effector downstream of various oncogenic pathways, such as PI3K/Akt and Ras/Raf/Mek/Erk (MAPK)." (PMID 37759234, 2023). "Discussion: Ezetimibe exhibits effects against CRC through the promotion of cancer cell death via mTOR signaling-dependent mitochondrial dysfunction, highlighting its potential value in CRC therapy." (PMID 36843944, 2023). "PIM kinases and PI3K/mTOR signaling pathways have been shown to play an important role in the regulation of cell cycle progression in multiple cancers, including pancreatic." (PMID 37943821, 2023).
cancer (continued). "Inhibition of PI3K/Akt/mTOR, MAPKs, Wnt/β-catenin, and inducing ROS production are the critical anti-cancer mechanisms of triterpenoid saponin." (PMID 36984763, 2023). "The PI3K/AKT/mTOR signaling pathway is a master regulator of cancer, which is frequently activated in various cancers and is considered a promising therapeutic target." (PMID 37303740, 2023). "The PI3K/AKT/mTOR pathway is a modulated signaling pathway in many cancer types, known to regulate different cellular processes such as cell survival, proliferation, growth, metabolism, angiogenesis, and metastasis." (PMID 37998723, 2023). "It is widely known that Wnt and mTOR pathways play a critical role in promoting the progression of cancer." (PMID 37393364, 2023). "In recent years, several mTOR inhibitors have been developed with the aim of treating different cancers." (PMID 37513916, 2023). "In this review, we introduce the activation of the PI3K/AKT/mTOR signalling pathway in cancer and the mechanisms by which PIKK members ATM, ATR, and DNA-PK repair DNA damage." (PMID 37489050, 2023). "We further identify YBX1 phosphorylation, downstream of the PI3K/mTOR pathway, restraining basal-like cancer cell proliferation." (PMID 36949044, 2023). "Of note, phosphatidylinositol-3 kinase (PI3K)/Akt/mammalian target of rapamycin (mTOR) signaling was found to enhance SCD1 expression as part of the mechanism of lipogenesis activation in cancer cells." (PMID 37373069, 2023). "They inhibit the mTOR pathway, which plays a crucial role in the cell growth, proliferation, angiogenesis, survival of malignant tumors, and the balance between effector T cells and regulatory T cells (Tregs)." (PMID 38203186, 2023). "The PI3K/AKT/mTOR pathway, frequently dysregulated in various cancers, plays a crucial role in protein synthesis through mTOR complexes 1 and 2 (mTORC1 and mTORC2)." (PMID 37755397, 2023). "mTOR is a serine/threonine kinase activated by various oncogenic signaling pathways and thus is overactive in cancer cells." (PMID 37332080, 2023). "Molecular studies indicated that these effects depended on the PI3K/AKT/mTOR pathway, which affects cancer malignancy." (PMID 37960338, 2023). "The PI3K/Akt/mTOR pathway is a critical regulatory axis for cell growth, survival, motility, and metabolism in both normal physiology and cancer." (PMID 37488620, 2023). "Multiple signaling pathways, classified into mTOR-dependent or mTOR-independent mechanisms, can regulate the activation of SREBPs in a lipid-independent manner in cancer." (PMID 36969840, 2023). "It is known that downregulation of MTOR can lead to growth progression, thus representing a possible strategy in cancer therapy." (PMID 38138609, 2023). "The abnormal activation of PI3K/mTOR signalling is found in some cancers, such as non-small-cell lung cancer, breast cancer, prostate cancer, Burkitt lymphoma, oesophageal adenocarcinoma, and colorectal cancer." (PMID 37368660, 2023). "Several studies have demonstrated that glutamine increases mTOR activity through phosphorylation in cancer cells." (PMID 37887353, 2023). "The phosphatidylinositol 3-kinase/protein kinase B/mammalian target of the rapamycin (PI3K/Akt/mTOR) pathway represents a critical signaling axis regulating various biological events in cancer, including proliferation, apoptosis, and angiogenesis." (PMID 37999532, 2023). "They discovered that cancer cells resistant to targeted medicines like trastuzumab had greater levels of mTOR signaling activity than cells responsive to targeted therapies." (PMID 38046946, 2023).
cancer (continued). "It has been reported that biological processes such as epithelial–mesenchymal transition (EMT), PI3K/AKT/mTOR signaling pathway, hypoxia, and cell cycle play important regulatory roles in cancer progression." (PMID 37535222, 2023). "The PI3K/AKT/mTOR pathway is dysregulated in almost all cancer types leading to uncontrolled growth." (PMID 38983593, 2023). "The MYCN silencing caused by BGA002 constitutes an innovative precision medicine approach, enabling the inhibition of mTOR to occur only in cancer cells, and leaving normal cells unaffected." (PMID 36765949, 2023). "Other reports on the anti‐cancer effects of monepantel place 4E‐BP1 along the mTOR signaling axis and induction of autophagy as critical processes underlying drug activity." (PMID 37148543, 2023). "The results of pathway analysis have shown that significant cancer-related (AKT/mTOR and c-Met pathways) and translation-related mechanisms (eIF4E release, translation factors) were enriched." (PMID 38072995, 2023). "The relationship between mTOR-dependent translation reprogramming and cancer in RiBi still needs further study." (PMID 38002277, 2023). "Adiponectin has an anticancer effect through the inhibition of mTOR signaling, and thus can be used for cancer treatment, including for PanNENs." (PMID 37444627, 2023). "The PI3K/AKT/mTOR pathway is widely dysregulated in cancer, and the evolutionarily conserved mTORC1 is a central therapeutic target." (PMID 37909334, 2023). "Targeted inhibition of PPT1 disrupts both the mTOR pathway and lysosomal function, signaling a new direction in cancer therapy." (PMID 38067206, 2023). "Another regulator for aerobic glycolysis in cancer cells is HIF1α, and this protein is positively enhanced by the activation of mTOR." (PMID 37259304, 2023). "It has been found that QRC inhibits the AKT/mTOR pathway exerting anti-cancer effect by reducing cancer cell viability and enhancing apoptosis and autophagy." (PMID 37447296, 2023). "Activation of mTOR promotes cell growth, and its inhibitors have been developed to treat cancer and cardiovascular disease." (PMID 37559091, 2023). "Inhibition of mTOR signaling leads to direct antitumor effects, such as the inhibition of cancer cell proliferation and induction of apoptosis." (PMID 37730584, 2023). "Natural compounds such as curcumin, fisetin, indole-3-carbinol, epigallocatechin gallate, celastrol, quercetin, and resveratrol were reported to target mTOR-mediated pathways and reported to be can be useful in various cancers." (PMID 36737760, 2023). "Several pathways, such as AMPK or PI3K/Akt/mTOR, are likely to be involved in the anti-cancer Met activity." (PMID 38003321, 2023). "mTOR is considered to be an important regulatory molecule in controlling the growth and proliferation of diabetes and cancer cells." (PMID 36830619, 2023). "The role of IGF-1 signaling is mainly explained by the mechanisms of increased proliferation, migration and cell survival via irradiated CAFs, which activate IGF-1R/AKT/mTOR signaling in cancer cells." (PMID 36835075, 2023). "Many clinical trials have been conducted to investigate the efficacy of mTOR inhibitors in the treatment of cancer, especially everolimus and LY3023414." (PMID 37368179, 2023). "For instance, in previously published cancer genomics papers, we proved the independence of genes involved in: chemokine signaling, apoptosis, evading apoptosis, and mTOR signaling." (PMID 38132440, 2023). "In these cancers, overexpressed Gαi1 and Gαi3 associated with receptor tyrosine kinases (RTKs) to mediate downstream Akt-mTOR cascade activation, thereby promoting cancer cell growth in vitro and in vivo." (PMID 36805440, 2023). "In many cancers, the mTOR signaling pathway is activated, which plays crucial parts in anti-apoptotic to trigger drug resistance." (PMID 36998461, 2023).
cancer (continued). "Through this complex, mTOR also plays a role in glucose metabolism, upregulating genes that allow cancer cells to utilize glucose under anaerobic conditions." (PMID 37240915, 2023). "SLC25A11 knockdown significantly reduced ATP production and inhibited cancer cell proliferation by blocking the mTOR phosphorylation and downregulation of c-Myc and eIF4B." (PMID 36902385, 2023). "Apart from Merkel cell polyomavirus (MCPyV) associated MCC, this cancer is linked in about 20% of cases to ultraviolet-induced mutational burden frequently causing aberrations in Notch and PI3K/AKT/mTOR signalling pathways." (PMID 37311987, 2023). "mTOR controls protein synthesis and supports cancer growth by activating S6 and 4EBP1/eIF4E/eIF4A-dependent translation programs." (PMID 36900235, 2023). "Our study shows that common pro-inflammatory and SASP-associated factors, TNFα and IL-6, were both significantly reduced by sirolimus treatment in both normal and early cancer, which confirms a role of mTOR signaling in promoting the secretion of SASP factors." (PMID 37904250, 2023). "The PI3K/AKT/mammalian target of rapamycin (mTOR) signalling pathway is one of the most essential intracellular pathways, and it can be regarded a key regulator for cancer." (PMID 35867269, 2023). "The expression of these genes and the invasive cancer cells of BCBM are significantly decreased when using a pharmacological inhibitor of the PI3K/AKT/mTOR signaling pathway." (PMID 35822637, 2023). "The PI3K/Akt/mTOR pathway is considered one of the most attractive targets for the development of anticancer agents, and it is constitutively activated in several cancer cells including NSCLC." (PMID 38033496, 2023). "Since the PI3K pathway is a driver of uncontrolled growth and spread of a variety of cancers, there are currently academic and clinical efforts in place to develop PI3K, AKT, and mTOR inhibitors as cancer therapeutics." (PMID 38983593, 2023). "Thirdly, the combination protocol (ICIs plus mTOR inhibitors) is a potential strategy to balance cancer immunology and graft tolerance." (PMID 36875077, 2023). "In cases of proliferative deregulation and in numerous different cancer types, mTOR signaling is triggered." (PMID 37999212, 2023). "Hyperactivated signaling of PI3K stimulates proliferation and reduces apoptosis in cancer, whereas inhibiting mTOR reduces cellular survival." (PMID 37584722, 2023). "Dysregulation of PI3K/AKT/mTOR signalling is frequently observed in human cancer and it is responsible for tumorigenesis, cancer progression, as well as intrinsic and acquired resistance to several treatments." (PMID 36765661, 2023). "PI3K is an important upstream protein of the PI3K-Akt-mTOR pathway and a well-established cancer therapeutic target." (PMID 37900167, 2023). "Most remarkably, wt-ANXA7 induced tissue-specific alterations in the autophagy-relevant insulin/PI3K/Akt/mTOR signaling cascade (including also FOXO and PTEN) that has a central role in carcinogenesis as one of the most mutated systems in human cancer." (PMID 37240163, 2023). "PI3K/AKT/mTOR pathway affects normal cellular processes, also have abnormal manifestations in many cancers." (PMID 36849137, 2023). "Essentially, ROS production elevation plays a role in cancer progressions, which are associated with cancer initiation and development through different signaling pathways (PI3/Akt/mTOR, PTEN, MAPK, VEGF/VEGFR, and MMPs)." (PMID 37210478, 2023).